SIRT1 (sirtuin 1)
Diseases named in the same sentence as SIRT1 in open-access papers (continued):
Sharing a sentence is not in itself a finding about the gene and the disease.
prostate carcinoma (continued). "On the other hand, other researchers analyzed a public database and found that Sirt1 expression was reduced in many other types of cancers, including glioblastoma, bladder carcinoma, prostate carcinoma and ovarian cancers as compared to the corresponding normal tissues." (PMID 21549004, 2011). "Although full functional role of this association is not yet understood, Ezh2 and SIRT1 both are highly expressed in prostate cancer and are associated with prostate cancer progression (and our unpublished data)." (PMID 21566744, 2008). "To explore the underlying mechanisms of increased vertebral cancellous bone indices in Sirt1+/Δ vs. WT male mice, we sought to investigate the AR, as SIRT1 was previously reported to deacetylase and inhibit AR function in prostate cells in the context of prostate cancer." (PMID 36568088, 2022). "This may suggest a differential role of SIRT1 in various sub-types of prostate cancer." (PMID 36291902, 2022). "In addition, SIRT1 overexpression has been shown to correlate with poor prognosis in several cancer types, including large B-cell lymphoma, prostate cancer, pancreatic cancer, gastric cancer, breast cancer, hepatocellular carcinoma, colorectal cancer and lung cancer." (PMID 25189993, 2014). "Conversely, SIRT1 deacetylates this site, inhibiting the interaction of PTEN with PDZ domain‐containing proteins, thus influencing the development of prostate cancer." (PMID 39778006, 2025). "Decreased expression of Sirt1 is observed in various cancers such as GBM, bladder cancer, prostate cancer, ovarian cancer, and breast cancer, where it exerts its tumor-suppressive effects." (PMID 40075208, 2025). "In nude mice bearing PC‐3 human prostate cancer xenografts, DOX treatment significantly downregulated NEU1 expression while concomitantly increasing SIRT1 protein levels in tumor lysates." (PMID 40411250, 2025). "In androgen-deprived prostate cancer, the activation of the FOXO-1/Sirt1 axis promotes tumor progression." (PMID 40075208, 2025). "Down-regulation of SIRT1 can continuously inhibit the proliferation of HCC and prostate cancer cells by inducing senescence or apoptosis." (PMID 38189049, 2023). "Its expression inhibits SIRT1 expression (via interaction with SIRT1 3’UTR), starvation- and SIRT1-induced autophagy, and angiogenesis of LNCaP and PC3 prostate cancer cells." (PMID 36291902, 2022). "Investigation of molecular pathways demonstrates downregulation of SIRT1 by MIR212 and subsequent inhibition of autophagy that are of importance for suppressing prostate cancer progression." (PMID 35317831, 2022). "In prostate cancer, ZEB1 and SIRT1 together bind to CDH1, promoting metastasis, while SIRT1 elicited EMT through Fra-1 over-expression in colorectal cancer." (PMID 35458763, 2022). "Similarly, it was also demonstrated that SIRT1 deacetylates AR and histone H3 at the promoter region of the prostate-specific antigen gene to suppress AR-mediated gene transcription, thereby inhibiting the proliferation of androgen-responsive LNCaP prostate cancer cells." (PMID 36291902, 2022). "In this section, we discuss the mechanistic roles of nuclear (SIRT1, 6, and 7), cytoplasmic (SIRT2), and mitochondrial sirtuins (SIRT3, 4, and 5) in breast and prostate cancer." (PMID 36291902, 2022). "Among these hsa-miR-204-5p target genes, SIRT1, SOX4, and RUNX2 exhibited a tumor-suppressive/oncogenic role in previous prostate cancer studies." (PMID 34512726, 2021). "SIRT1 also prompts cancer cell migration and metastasis in vivo and in vitro by combining with ZEB1 to inhibit CDH1 expression in prostate cancer cells." (PMID 32210140, 2020).
prostate carcinoma (continued). "Our previous study also showed that TLX can play a role in suppression of oncogene-induced senescence in prostate cancer cells via its direct repression of p21/CDKN1A and SIRT1." (PMID 29555975, 2018). "SIRT1 induces the EMT by cooperating with ZEB1; together, these components function to enhance cell migration and metastasis in prostate cancer." (PMID 29531814, 2018). "We showed in prostate cancer cells that RARRES1 is able to induce autophagy, decrease mechanistic target of rapamycin (mTOR) and increase Sirtuin 1 (SIRT1), two important regulators of energy homeostasis." (PMID 30557378, 2018). "Then, we applied subcutaneously implanted tumor model in C57BL/6 mice to determine the effect of MSCs-Sirt1 on RM-1 and PC2 prostate cancer cells growth in vivo." (PMID 27764779, 2016). "It has also been shown that SIRT1 induces EMT and that reduction of SIRT1 decreases prostate cancer cell migration in vitro." (PMID 26988912, 2016). "SIRT1 is also found over-expressed in many cancers and frequently NAMPT is concurrently over-expressed with SIRT1, which is important for prostate cancer cell survival and stress response." (PMID 25146220, 2014). "Our observation that SIRT1 is highly expressed in HCC cell lines is consistent with that of others who reported that SIRT1 is overexpressed in liver, colon, breast, and prostate cancers and squamous cell carcinomas." (PMID 22479397, 2012). "Interestingly, the member SIRT1 induces EMT and enhances prostate cancer cell migration and metastasis." (PMID 36980828, 2023). "In addition, SIRT1 overexpression led to enhanced expression of MMP2, promoting cell invasion in prostate cancer cells." (PMID 35252011, 2022). "Regardless of its predominant expression in prostate cancer cells, SIRT1 has been demonstrated to either promote or suppress prostate cancer via different mechanisms." (PMID 36291902, 2022). "Even though SIRT1 does not represent a direct target of mir-221, in prostate cancer cell transfected with mir-221, the inhibitor SIRT1 protein was up-regulated." (PMID 34199293, 2021). "SIRT1 is highly expressed in several cancers, including prostate carcinoma, acute myelogenous leukemia, colon cancer, and some nonmelanoma skin cancers." (PMID 31817470, 2019). "Recently, we have demonstrated that TLX, which is upregulated in prostate cancer, can promote its initiation and progression by repression of oncogene-induced senescence via its differential co-regulation of senescence-regulatory genes CDKN1A and SIRT1." (PMID 29555975, 2018). "Epigenetic regulation by SIRT1, a multifaceted NAD+-dependent protein deacetylase, is one of the most common factors modulating cellular processes in a broad range of diseases, including prostate cancer (CaP)." (PMID 26988912, 2016). "Interestingly, MSCs-Sirt1 suppressed RM-1 and PC2 prostate cancer growth in vivo, in contrast to the tumor promoting effect of MSCs." (PMID 27764779, 2016). "Indeed, a previous study has observed the correlation between SIRT1 expression level and the CPT sensitivity in prostate cancer cells, although in very limited number of cell lines." (PMID 26008972, 2015). "We have previously identified SIRT1 as a positive regulator of epithelial-to-mesenchymal transition (EMT), cell invasion, and metastatic growth of prostate cancer cells, and put forward SIRT1 as a potential therapeutic target to reverse EMT and to prevent prostate cancer progression." (PMID 25189993, 2014). "Induced SIRT1 overexpression in prostate cancer cell lines resulted in almost complete absence of H2A.Z." (PMID 24127549, 2013). "SIRT1 and SIRT3 may be up- or downregulated depending on the cancer type, acting either as oncogenes (e.g., colorectal or oral cancer), or tumor suppressors (e.g., SIRT1 in bladder cancer, SIRT1 and SIRT3 in breast and prostate cancer)." (PMID 32344886, 2020).
prostate carcinoma (continued). "Likewise, SIRT1 is recruited to the promoter of E-cadherin and acts as a co-suppressor with ZEB1 to synergistically inhibit E-cadherin transcription, thus promoting EMT in prostate cancer." (PMID 31068761, 2019). "Importantly, two mechanisms that could potentially regulate PGC-1α in prostate cancer rely on AMP kinase (AMPK) and the sirtuin SIRT1." (PMID 29629336, 2018). "Several reports have shown that SIRT1 acts as a tumor promoter: SIRT1 enhanced the migration of melanoma cells by regulating lamellipodial extension, and cooperated with ZEB1 to induce the epithelial-mesenchymal transition (EMT) and increase prostate cancer cell migration and invasion." (PMID 27081083, 2016). "Although the mechanisms were not fully elucidated, studies reported that SIRT1 promotes cell growth and chemoresistance in PC3 and DU145 prostate cancer cells as well as the migration and invasion of DU145 prostate cancer cells." (PMID 36291902, 2022).
colorectal cancer (141 papers, 2006 to 2026). A primary or metastatic malignant neoplasm that affects the colon or rectum. "In contrast, the acceleration of the senescence of colorectal cancer (CRC) cells by 500 μM ASA was found to be associated with a mechanism involving SIRT1 and phospho-AMPK upregulation." (PMID 41154546, 2025). "These analyses did not reveal any sex-specific differences in the association between SIRT1 polymorphisms and colorectal cancer occurrence." (PMID 40507674, 2025). "Increasing evidence suggests the significance of SIRT1 gene polymorphisms in modulating colorectal cancer (CRC) risk." (PMID 40507674, 2025). "Despite these limitations, this study offers a solid foundation for further exploration of the role of SIRT1 polymorphisms in colorectal cancer susceptibility and supports the growing relevance of personalized prevention strategies in oncology." (PMID 40507674, 2025). "We found that high SIRT1 expression at stage (I + II) in 78 male patients with colorectal cancer was associated with poor prognosis for relapse-free survival (RFS) [hazard ratio (HR): 2.11, log-rank p = 0.025]." (PMID 38539819, 2024). "The forthcoming index shows that overexpression of SIRT1 is associated with poor prognosis in many types of solid tumors, including breast, prostate, bladder, and colorectal carcinoma." (PMID 38539819, 2024). "SIRT1 is upregulated in colorectal cancer samples, and clinical analysis indicated a vital association between high SIRT1 expression and poor outcome in colorectal-cancer patients." (PMID 37490168, 2023). "Our results are in line with previously reported data showing that miR-486-5p was down-modulated in the tumor tissue and implicated in the control of the CSC phenotype of colorectal cancer patients and in liver cancer through Sirtuin 1 mRNA regulation." (PMID 35337095, 2022). "We investigated SIRT1’s specific role in colorectal tumorigenesis by studying SIRT1 polymorphisms in relation to colorectal cancer (CRC) risk by microsatellite instability (MSI) and CpG island methylator phenotype (CIMP) status." (PMID 32098999, 2020). "We used SIRT1 variants as time-independent indicators of SIRT1 involvement in carcinogenesis and we studied two tagging SIRT1 variants in relation to colorectal cancer (CRC) risk." (PMID 30410074, 2018). "Regarding colorectal cancer, a couple of studies have reported significant associations between high SIRT1 expression and poor overall survival (OS) and/or disease-free survival." (PMID 28977971, 2017). "A high c-MYC and SIRT1 protein co-expression has been demonstrated to be associated with malignant transformation of specific colorectal cancer subtypes." (PMID 29383100, 2017). "First, the relatively small sample size may have limited the statistical power to detect significant associations between SIRT1 polymorphisms and colorectal cancer risk." (PMID 40507674, 2025). "Given that elevated BMI is a well-established risk factor for colorectal cancer, the potential influence of SIRT1 polymorphisms on body weight regulation may be an important intermediate factor in understanding genotype–phenotype–disease associations." (PMID 40507674, 2025). "Similarly, increased SIRT1 expression has been associated with an unfavorable prognosis in colorectal cancer, esophageal squamous cell carcinoma, and gastric cancer." (PMID 39845948, 2024). "Therefore, we investigated the role of FAK or cytoskeletal organization on the resveratrol-induced up-regulation of Sirt1 expression (arrows) and of the possible associated mechanism in colorectal cancer cells." (PMID 28953264, 2017).
colorectal cancer (continued). "In addition, SIRT1 expression in colorectal cancer has also been associated with microsatellite instability and the CpG island methylator phenotype, both of which have been linked to prognosis and survival in colorectal cancer." (PMID 28977971, 2017). "This review centers on SIRT1’s complex role in gastrointestinal tumors, especially esophageal cancer (EC), gastric cancer (GC), and colorectal cancer (CRC), highlighting its dual potential as both a tumor promoter and suppressor." (PMID 40567502, 2025). "While previous research has extensively explored the role of SIRT1 in gastric and colorectal cancers, our study offers novel insights by directly comparing SIRT1 expression across three major gastrointestinal cancers: gastric, colon, and rectal cancers." (PMID 41020376, 2025). "Although previous studies have shown high expression of SIRT1 in colorectal cancer, the results of our clinical samples showed low expression of SIRT1 in colorectal cancer, a finding that was further validated by immunohistochemistry and Western blotting." (PMID 41020376, 2025). "For instance, UBE2V1-mediated ubiquitination and degradation of Sirt1 promote colorectal cancer metastasis through epigenetic suppression of autophagy." (PMID 41446875, 2025). "Western blotting (WB) showed that the protein level of SIRT1 was significantly upregulated in samples from patients with GC, whereas it was downregulated in patients with colorectal cancer." (PMID 41020376, 2025). "SIRT1 expression in gastrointestinal tumors is tissue‐specific (upregulated in GC, downregulated in colorectal cancer)." (PMID 41020376, 2025). "Ropivacaine induces ferroptosis to upregulate the cisplatin-sensitivity of human colorectal cancer by the sirtuin 1 (SIRT1)/ nuclear factor erythroid 2-related factor 2 (Nrf2) pathway." (PMID 41460836, 2025). "A decrease in SIRT1 activity can inhibit cancer cell proliferation, while the active metabolite of vitamin D, 1,25(OH)2D3, activates SIRT1 and exerts an antiproliferative effect on colorectal cancer cells." (PMID 40284214, 2025). "On the contrary, miR-29b is downregulated in oxaliplatin-resistant colorectal cancer cells, where SIRT1 levels are correspondingly elevated." (PMID 40871106, 2025). "The influence of the SIRT1 polymorphism on the risk of developing CRC, specifically MSI CRC (microsatellite instability-positive colorectal cancer), was also demonstrated by Hriz (2020)." (PMID 40507674, 2025). "In colorectal cancer, Ube2v1 inhibits Sirt1, reduces H4K16 acetylation, suppresses autophagy, and promotes EMT and invasion, indicating unfavorable prognosis." (PMID 41213956, 2025). "In tissues, SIRT1 expression was up‐regulated in GC but down‐regulated in colorectal cancer (CC and RC) tissues (p < 0.05)." (PMID 41020376, 2025). "This also confirms why the expression of SIRT1 was relatively low in colorectal cancer in our study." (PMID 41020376, 2025). "The nuclear receptor NR3C2 induces SIRT1 expression in colorectal cancer (CRC), forming an effective NR3C2–SIRT1 axis." (PMID 41425553, 2025). "The lncRNA H19, which has oncogenic properties in colorectal cancer, mediates 5-fluorouracil resistance by sponging miR-194–5p to elevate SIRT1 expression, thus promoting autophagy-induced resistance to 5-fluorouracil in colorectal tumors." (PMID 39403142, 2024). "A depletion of SMURF2 results in an upregulation of SIRT1, which fosters the formation and growth of colorectal cancer both in vitro and in vivo." (PMID 39697237, 2024). "MiR-653–3p promotes genomic instability, proliferation, migration, and chemoresistance in colorectal cancer cells by inhibiting SIRT1 and activating the TWIST1 signaling pathway." (PMID 39403142, 2024). "When combined with the SIRT1 protein, curcumin can promote the effects of SIRT1 on the proteasomal degradation of colorectal cancer and exert anti-tumor effects." (PMID 37719857, 2023).